NECTIN4 (nectin cell adhesion molecule 4)
Diseases named in the same sentence as NECTIN4 in open-access papers (continued):
Sharing a sentence is not in itself a finding about the gene and the disease.
cancer (continued). "Their findings showed that recombinant MV specifically binds to Nectin-4 expressed on the surface of cells and additionally that it can reveal anti-cancer effects in several other malignancies, including CRC." (PMID 36553083, 2022). "This statement is strongly supported by studies reporting Nectin-4 overexpression correlating with disease advancement and a worse prognosis in other cancer types." (PMID 36553083, 2022). "Analysis of the protein and mRNA products of 84 cancer-related human genes identified Nectin-4 and CapG as G-quadruplex-controlled genes whose mRNAs harbor non-canonical G-quadruplex structures on their 5′UTR region." (PMID 35801908, 2022). "In-depth understanding of this biomarker is beneficial to the study of Nectin-4-related pathophysiological processes in cancer." (PMID 35614462, 2022). "In our study, we firstly demonstrated the aberrant overexpression of Nectin4 on both primary and metastatic solid tumors and FAP on cancer-associated fibroblasts." (PMID 36479116, 2022). "It gives an opportunity to utilize the oncolytic properties of MV in the treatment of Nectin-4-induced cancer." (PMID 36553083, 2022). "Currently, a variety of therapeutic strategies against Nectin-4 are used for cancer treatment, including bioactive/synthetic compounds (e.g., nanoquinacrine), antibody–drug conjugates (ADCs), and oncolytic viruses." (PMID 35614462, 2022). "The analysis of Nectin-4 expression (2394 cases of cancers from 34 different histology), published by Challita-Eid and colleagues, showed that 69% of cancer specimens were positive for Nectin-4." (PMID 35164713, 2022). "Nectin-4 is upregulated in many types of cancers, such as breast, pancreatic, lung, gallbladder, ovarian, gastric, and bladder cancers." (PMID 33795719, 2021). "To further investigate the effects of NECTIN4 on cancer cell proliferation, we transfected cells with siRNA and then assessed cell proliferation." (PMID 33808400, 2021). "Because NECTIN4 expression is enhanced in several types of cancers, it is expected to be a novel target of cancer therapy." (PMID 33808400, 2021). "In several types of cancer cells, overexpression of NECTIN4 increases the viable cells and inhibition of NECTIN4 decreases it." (PMID 33808400, 2021). "Nectin-4 further inhibits ferroptosis of epithelial and cancer cells by clustering each cell to survive under a matrix-detached condition." (PMID 33795719, 2021). "In each subgroup, most carcinomas showed expression of Nectin-4, including 100% (14/14) of the SCC cohort, 91% (20/22) of the AC/UrC cohort, and 82% (69/84) of the Sq-BLCA cohort." (PMID 34768978, 2021). "Another solid tumor target, nectin-4 is a calcium-independent cell adhesion molecule overexpressed in bladder and other cancers, and the target for the recently approved enfortumab vedotin (AGS-22M6E, PadcevTM)." (PMID 32111076, 2020). "Urothelial cancer is one such cancer, and clinical trials of enfortumab vedotin, a drug-conjugated anti-NECTIN4 antibody, are ongoing." (PMID 32824340, 2020). "Nectin-4 is also broadly expressed in many normal epithelial tissues in low-to-moderate levels; however, its expression levels in cancers are much higher, resulting in an acceptable safety profile and therapeutic window for enfortumab vedotin." (PMID 32111076, 2020). "As EV is an antibody-drug conjugate targeting Nectin-4, the expression of Nectin-4 in cancer cells is necessary for its cytotoxic effect." (PMID 32751328, 2020). "Nectin cell adhesion molecule 4 (NECTIN4) has attracted attention as a potential therapeutic target for some cancers." (PMID 32824340, 2020). "Further translational studies are needed to investigate the role of membranous Nectin-4 expression during cancer progression and to reveal potential interactions with the immune system or therapeutic interventions." (PMID 31572728, 2019). "It has been reported that Nectin-4 is overexpressed in several human cancers, including lung, and breast cancer." (PMID 29066719, 2017).
cancer (continued). "On the other hand, there was limited expression of Nectin-4 in non-cancer tissues including islet cells, acinar cells and normal gland." (PMID 25888293, 2015). "Immunofluorescence studies confirmed IHC and revealed a cytoplasmic expression of Nectin-4 and a clear localization at intercellular junctions between carcinoma cells (white arrow)." (PMID 17474988, 2007). "Nectin-4 is primarily expressed in the placenta, skin, lungs, and urinary system, with minimal expression in most adult tissues, making it an appealing target for cancer diagnosis and monitoring." (PMID 40774696, 2025). "The most extensively studied nectin-4 also shows prognostic potential in many cancers." (PMID 40244005, 2025). "Flow cytometry analysis confirmed differential Nectin-4 expression across the two cancer types." (PMID 40542857, 2025). "Furthermore, an in vivo study using a T24 nectin-4 xenograft model demonstrated immune cell recruitment to cancer tissues and their activation." (PMID 39891702, 2025). "Außerdem wurde auf dem Blasenkrebs-Kongress der American Association of Cancer Research (AACR) 2024 berichtet, dass Glitazone die Nectin4-Expression hochregulieren können und somit das therapeutische Fenster der Nectin4-basierten Therapien vergrößern könnten." (PMID 40067496, 2025). "Nectin-4 is primarily expressed in the placenta, skin, lungs, and urinary system, with minimal expression in most normal adult tissues, making it an attractive biomarker for cancer diagnosis and monitoring." (PMID 40542857, 2025). "HER2 receptor, Nectin‐4, Trop‐2, Tissue factor (TF‐011), and folate receptor (FRα) are all cancer cell surface proteins whose expression is significantly upregulated in their respective cancers, making them prime candidates leading to FDA‐approved ADC therapeutics." (PMID 40551322, 2025). "The proportion of nectin-4-positive patients mightbe lower for other cancer types, and the changes in the protein levelupon metastatic spread are not yet explored." (PMID 41081542, 2025). "Nectin-4 has been identified as a potential biomarker of cancer progression and prognosis." (PMID 39813112, 2025). "This suggests that the combination of short-course treatment with PPARγ agonists and NECTIN4-targeting anti-cancer therapy may be safe and feasible in the clinical setting, and warrants further investigation." (PMID 40931013, 2025). "Notably, Nectin-4 overexpression was predominantly cytoplasmic in poorly differentiated tumors, whereas membranous staining was more pronounced in well-differentiated carcinomas and in the cell membranes of normal epithelial tissue." (PMID 40699695, 2025). "More research is required to explore the serological value of soluble Nectin-4 in other cancers." (PMID 38606099, 2024). "Furthermore, we queried The Cancer Genome Atlas (TCGA) data sets (10,712 patients across 32 cancer types) for NECTIN4 CNVs." (PMID 38657187, 2024). "Nectin-4 is a protein that is found in higher levels in UC and other types of cancer." (PMID 39723374, 2024). "In addition, many new drugs targeting Nectin-4 for the treatment of malignant tumors have entered clinical trials, with the aim of exploring potential new indications." (PMID 38606099, 2024). "Notably, Nectin-4 is frequently overexpressed in several cancer types, including urothelial cancer (UC)." (PMID 39598456, 2024). "As well as these potential applications in cancer diagnosis, increased levels of soluble Nectin-4 in serum may contribute to the diagnosis and monitoring of asthma and may also represent a new biomarker for opioid dependence." (PMID 38606099, 2024). "Notably, recent studies have shown that Nectin‐4 is overexpressed in various malignant tumors, contributing to disease progression and poor prognosis in cancers such as urothelial cancer, breast cancer, pancreatic cancer, TNBC, and bladder cancer." (PMID 39070179, 2024).
cancer (continued). "It is expected that Nectin-4 will continue to be a focus of attention in the field of medical imaging, offering promising opportunities for improved diagnosis and monitoring of various diseases, particularly cancer." (PMID 38606099, 2024). "This could benefit cancer patients with high expression of Nectin-4, such as those with locally advanced or metastatic urothelial carcinoma (la/mUC)." (PMID 38606099, 2024). "Another study found aberrant overexpression of FAP on cancer-associated fibroblasts, suggesting that FAP and Nectin4 could serve as promising targets for safe and effective CAR-T therapy in malignant solid tumors." (PMID 38063927, 2023). "Therefore, Nectin-4-targeted therapy is a potent strategy for treating cancers with high Nectin-4 expression." (PMID 37345201, 2023). "Current literature suggests that nectin-4 has a role in cancer progression and may have prognostic and therapeutic implications." (PMID 38288120, 2023). "The authors concluded that nectin-4 could serve as a marker for distinguishing OC from benign lesions and for monitoring the cancer treatment." (PMID 37568798, 2023). "The current study is the first report of high serum nectin-4 levels in a non-cancer disorder." (PMID 37554937, 2023). "Therefore, Nectin-4 has potential to be the most promising therapeutic target and prognostic biomarker for Nectin-4-overexpressing cancer, including TNBC." (PMID 35614462, 2022). "In addition, the new BTC is also a putative anti-cancer drug against other Nectin-4-expressing cancers." (PMID 36553083, 2022). "The increasing knowledge of the pathogenesis and molecular pathways underlying cancer development and progression is leading the introduction of target therapies, such as the recently approved FGFR inhibitor Erdafitinib, or the anti-nectin 4 antibody drug-conjugate Enfortumab vedotin." (PMID 35269424, 2022). "Nectin-4 has been identified as a biomarker of cancer stem cells (CSCs)." (PMID 36553083, 2022). "Also, the expression level of the nectin-3 gene was lower and that of nectin-4 was higher in HCC tissues compared to in normal tissues adjacent to cancer from all patients (p < 0.05)." (PMID 36059705, 2022). "The activity of this ADC is under investigation in other cancers known to express Nectin-4." (PMID 36553083, 2022). "Importantly, an increasing number of studies have demonstrated that Nectin-4 is specifically overexpressed in various cancers." (PMID 35953862, 2022). "Indeed, changes in NECTIN4 levels reportedly alter the status of cell adhesion, leading to changes in the spheroid formation and growth of cancer cells." (PMID 33808400, 2021). "Enfortumab vedotin-ejfv is indicated for cancers expressing Nectin-4, such urothelial cancers." (PMID 32050446, 2020). "Nectin-4 is found overexpressed on the surface of tumor cells in some ovarian or lung cancers and could therefore be used for treatment of cancers expressing this receptor." (PMID 33207797, 2020). "So far, Nectin-4 has been considered to be overexpressed in several types of cancer." (PMID 32751328, 2020). "However, the detailed mechanism of Nectin-4 in promoting cancer progression still deserved further investigation." (PMID 31043861, 2019). "Moreover, in addition to its membranous form, the soluble Nectin-4 can also be detected in serum from cancer patients, and therefore the serum level of soluble Nectin-4 can serve as important prognostic risk factor for the patients." (PMID 31043861, 2019). "In addition, the PI3K/AKT signaling pathway is involved in the Nectin-4-mediated promotion of cancer cell proliferation." (PMID 31043861, 2019). "In addition, since certain cancers, (breast, lung and ovarian cancer) overexpress nectin-4, it has been described as a new biomarker for these cancer types." (PMID 30217189, 2018). "Nectin-4 expression was observed in six of the 10 cancer cell lines tested." (PMID 27090874, 2016). "Nectin-4 was abundant and expressed mainly in the plasma membrane and cytoplasm of cancer cells." (PMID 25888293, 2015).
cancer (continued). "Recent studies have also suggested some roles for Nectin-4 in several human cancers." (PMID 25888293, 2015). "Taken together, Nectin-4 may be a critical factor contributing to the progression in certain human cancers." (PMID 25888293, 2015). "Our screen identified a cell adhesion molecule PVRL4 (poliovirus receptor-like 4), also known as Nectin-4, which we demonstrate to be a potent mediator of anchorage-independent colony formation in normal epithelial and cancer cells alike." (PMID 23682311, 2013). "However, with more in-depth research on the Nectin-4 target, ADCs that target Nectin-4 could broaden our understanding of its role in cancer and its potential as therapeutic targets." (PMID 39813112, 2025). "However, despite the recent evidence of Nectin-4 overexpression in cancer and its therapeutic efficacy, the biological significance of Nectin-4 in EC and its clinical potential value as a therapeutic target remain unknown." (PMID 37345201, 2023). "Given the pleiotropic role of SFKs in cellular events, including cell cycle progression, cell survival, adhesion, and migration, and in pathophysiological disorders, including cancers, activation of SFKs by nectin-4 could contribute to cancer transformation from multiple pathways." (PMID 38288120, 2023). "Interestingly, Nectin-4 is overexpressed in many types of cancers, including UC." (PMID 36139571, 2022). "Thus, NECTIN4 is expected to be a novel therapeutic target for cancer." (PMID 35256687, 2022). "In the period 2015–2021, cancer continued to be the main target, but there was increasing interest in discovering new ways and new targets, reflected, for example, by a new class of biological as a fragment of an antibody (Efgartigimod), the first therapy targeting Nectin-4 (Enfortumab Vedotin)." (PMID 36140426, 2022). "Thus, NECTIN4 is now attracting attention as a potential target for cancer treatment." (PMID 35256687, 2022). "Thus, NECTIN4-targeted therapy may serve as a potent strategy for treating cancers with high NECTIN4 expression." (PMID 33478111, 2021). "Similar to these reports, in the present study, NECTIN4 inhibition attenuated the cell–cell attachment of A431 cells in the 2D culture and loosened the aggregation of spheroids, implying that NECTIN4 also regulates cell–cell interactions in cSCC and may contribute to the growth of cancer cells." (PMID 33808400, 2021). "Moreover, the abnormal expression of Nectin-4 in cancer cells could also regulate the cellular functions and angiogenesis." (PMID 31043861, 2019). "In 18% of cancer metastases, strong Nectin-4 expression could be observed." (PMID 31572728, 2019). "Nectin-4 blockade may enhance the effect of the inhibition of VEGF in cancer treatment." (PMID 25888293, 2015). "The engagement of TIGIT with its binding partners, poliovirus receptor (PVR) (CD155), nectin-2 (CD112), and nectin-4 (PVRL4)—plays a pivotal role in modulating immune reactions and the evolution of cancer." (PMID 40777027, 2025). "By binding to nectin-4 expressed on cancer cells, the antibody forms an ADC-nectin-4 complex, allowing the complex to enter cancer cells and become available for lysosomal transfer." (PMID 39891702, 2025). "The Nectin-4 NDC exhibited excellent specificity and high cellular uptake in cancer cells with elevated Nectin-4 expression, and effectively inhibited GC progression in vivo in a dose-dependent manner." (PMID 41019528, 2025). "We observed a significant increase in the expression of cancer stem cell markers, including CD44, VEGFA, ITGB1, ALDH1A3, SOX9 and NECTIN4, and enrichment in stemness-related pathways, such as the hedgehog, PI3K-AKT-mTOR, and WNT signaling pathways." (PMID 38892065, 2024). "Transcriptional analysis has shown that Nectin-4 and CD137 are co-expressed in a variety of cancers." (PMID 38606099, 2024).
cancer (continued). "In addition, since nectin-4 has been proposed as a new therapeutic target for antibody-based cancer treatment and oncolytic measles virotherapy, which utilizes nectin-4 as a receptor, the scFvs could also be useful for screening suitable candidates to receive such nectin-4-targeted treatments." (PMID 38288120, 2023). "ADAM17 (a disintegrin and metalloproteinase 17)/TACE (a TNFα-converting enzyme) overexpressed in many cancers, including CRC, is capable of Nectin-4 cleavage under hypoxic conditions." (PMID 36553083, 2022). "Because BNectin-4 is a protein involved in cell–cell adhesion and is present at high levels in various malignant tumor cells, BNectin-4-targeting BT8009 can bind to Nectin-4 on breast cancer MDA-MB-468 cells and kill them." (PMID 35890274, 2022). "Nectin-4 activates the PI3K-AKT signaling through the Rac small G protein signaling and the Wnt-β-catenin signaling for cancer cell proliferation and metastasis." (PMID 33795719, 2021). "On the other hand, the vcMMAE-conjugated antibody potently induced cancer cell death with IC50 of 0.25 nM (37.8 ng/mL) for T47D cells, implying efficient internalization of the ADC upon the binding to nectin-4." (PMID 32111076, 2020). "Furthermore, direct targeting of Nectin-4 may have therapeutic potential for cancer treatment." (PMID 25888293, 2015). "Nectin-4 was expressed in one of four cell lines derived from prostate (LnCaP) and bladder (RT112) carcinomas." (PMID 17474988, 2007). "Antibody-drug conjugates (ADCs), such as human epidermal growth factor receptor 2 (HER-2), nectin cell adhesion molecule 4 (Nectin-4), and epidermal growth factor receptor (EGFR)-targeted ADC drugs, have been explored recently and have been shown to be effective in several human cancers." (PMID 41425706, 2025). "Carcinomas were characterized by upregulated B7-H4 and NECTIN4 as compared to non-epithelial cancers." (PMID 40788962, 2025). "Additionally, expressions of EGFR, NECTIN4, TROP2, HER2, and HER3, the molecules which are considered to serve as therapeutic targets of cancers, were assessed." (PMID 39582977, 2024). "In the field of oncology, currently approved ADCs target specific proteins overexpressed by cancer cells, such as HER2, trophoblast cell surface antigen 2 (Trop2), Nectin‐4, and EGFR in solid tumors, and CD19, CD22, CD33, CD30, and CD79b in hematologic malignancies." (PMID 39070179, 2024). "Furthermore, cancer antigens, such as HER2, Nectin-4, or TROP2, highly selectively expressed on the surface of cancer cells act as a receptor for receptor-mediated endocytosis (RME) using mAbs against such antigens." (PMID 36546903, 2022). "Detailed analysis showed that Nectin-4 was exclusively expressed in carcinoma cells and absent from myoepithelial and stromal cells (data not shown)." (PMID 17474988, 2007). "However, Nectin‐4 expression in primary cancers in an era before availability of EV had no impact on survival." (PMID 39801278, 2025). "However, certain studies have confirmed the continued high expression of Nectin-4 in new tissue specimens after cancer recurrence, which does not support a decrease in antigen levels as key to the emergence of resistance to EV." (PMID 38606099, 2024). "The precise mechanism by which Nectin-4 participates in cancer progression is not clear." (PMID 39337530, 2024). "In addition, our study does not include correlative data on NECTIN4 CNVs and responses to EV in other cancer entities, as mUC is the only approved standard-of-care setting for EV to date." (PMID 38657187, 2024). "However, so far, the molecular mechanism of how Nectin-4 is involved in the poor prognosis of cancer is not clear, and thus our study also warrants further investigations to elucidate the relationships among Nectin-4, cell size, and cancer malignancy." (PMID 38062106, 2023). "Lastly, both Nectin-2 and Nectin-4 were not specific to the cancer tissues, which could impact on the results of this study." (PMID 37174031, 2023).